DIS3 (DIS3 exosome endoribonuclease and 3'-5' exoribonuclease)
Description:
Putative catalytic component of the RNA exosome complex which has 3'->5' exoribonuclease activity and participates in a multitude of cellular RNA processing and degradation events. In the nucleus, the RNA exosome complex is involved in proper maturation of stable RNA species such as rRNA, snRNA and snoRNA, in the elimination of RNA processing by-products and non-coding 'pervasive' transcripts, such as antisense RNA species and promoter-upstream transcripts (PROMPTs), and of mRNAs with processing defects, thereby limiting or excluding their export to the cytoplasm. The RNA exosome may be involved in Ig class switch recombination (CSR) and/or Ig variable region somatic hypermutation (SHM) by targeting AICDA deamination activity to transcribed dsDNA substrates. In the cytoplasm, the RNA exosome complex is involved in general mRNA turnover and specifically degrades inherently unstable mRNAs containing AU-rich elements (AREs) within their 3' untranslated regions, and in RNA surveillance pathways, preventing translation of aberrant mRNAs. It seems to be involved in degradation of histone mRNA. DIS3 has both 3'-5' exonuclease and endonuclease activities.
Synonyms: KIAA1008; RRP44; dis3p; EXOSC11; 2810028N01Rik
Tractability: Small molecule: a structure with a bound ligand is known. PROTAC: ubiquitination databases record sites on it; its protein half-life has been measured.
Target class: Enzyme; Hydrolase
Gene: Protein-coding gene on chromosome 13 (72,752,169 to 72,782,096, reverse strand). Ensembl gene ENSG00000083520.
Subcellular location: Cytoplasm; Nucleus, nucleolus; Nucleus, nucleoplasm; Nucleus
Subcellular location (Human Protein Atlas): Nucleoplasm; Cytosol
Pathways (Reactome):
Metabolism of RNA: Butyrate Response Factor 1 (BRF1) binds and destabilizes mRNA; KSRP (KHSRP) binds and destabilizes mRNA; Major pathway of rRNA processing in the nucleolus and cytosol; Nuclear RNA decay; Tristetraprolin (TTP, ZFP36) binds and destabilizes mRNA; mRNA decay by 3' to 5' exoribonuclease
Cellular responses to stimuli: ATF4 activates genes in response to endoplasmic reticulum stress
Gene Ontology:
Molecular function: 3'-5'-RNA exonuclease activity; endonuclease activity; guanyl-nucleotide exchange factor activity; protein binding; RNA binding; RNA nuclease activity
Biological process: CUT catabolic process; RNA catabolic process; RNA processing; rRNA catabolic process; nuclear mRNA surveillance of mRNA 3'-end processing; nuclear-transcribed mRNA catabolic process, deadenylation-dependent decay; rRNA processing; nuclear-transcribed mRNA catabolic process
Cellular component: cytoplasm; cytosol; membrane; nuclear exosome (RNase complex); nucleolus; nucleoplasm; nucleus; cytoplasmic exosome (RNase complex); exosome (RNase complex)
Genetic constraint (gnomAD): Loss-of-function variants: 94 observed, 103.74 expected, observed/expected ratio (o/e) 0.91, 90% interval 0.77 to 1.08. The upper end of that interval is the gene's LOEUF score, 1.08, which puts it in group 4 of 6, group 1 being the genes least tolerant of losing a copy. Missense variants: 1,051 observed, 1,114.3 expected, observed/expected ratio (o/e) 0.94, 90% interval 0.9 to 0.99. Synonymous variants: 385 observed, 374.36 expected, observed/expected ratio (o/e) 1.03, 90% interval 0.94 to 1.12.
Homologues: Orthologues: chimpanzee DIS3 (99% identical), macaque DIS3 (98% identical), dog DIS3 (95% identical), rabbit DIS3 (95% identical), pig DIS3 (94% identical), guinea pig DIS3 (93% identical), mouse Dis3 (91% identical), rat Dis3 (87% identical), tropical clawed frog dis3 (79% identical), zebrafish dis3 (74% identical), Drosophila melanogaster Dis3 (56% identical), Caenorhabditis elegans dis-3 (45% identical). Paralogues in human: DIS3L (37% identical), DIS3L2 (26% identical).
Diseases named in the same sentence as DIS3 in open-access papers:
DIS3 is named in the same sentence as 31 diseases in open-access papers, as found by Europe PMC text mining. Sharing a sentence is not in itself a finding about the gene and the disease. The quoted sentences say what the papers report.
multiple myeloma (26 papers, 2013 to 2026). "In multiple myeloma (MM), recurrent mutations of the DIS3 gene, which encodes the major nuclear catalytic subunit of this complex, illustrate the importance of these pathways during the ultimate step of B cell differentiation into plasma cells (PCs)." (PMID 38287115, 2024). "DIS3 somatic mutations have been shown to disturb RNA metabolism of myeloma cells, inducing ncRNA accumulation." (PMID 38287115, 2024). "Multiple myeloma-associated DIS3 mutations disrupt proper RNA degradation and processing in both mammalian cells and budding yeast mutant cells." (PMID 36861343, 2023). "Mutations in the gene DIS3, which encodes the catalytic component of the RNA exosome, are commonly found in patients diagnosed with multiple myeloma, suggesting a link between RNA exosome function and disease pathology." (PMID 36861343, 2023). "As one exception, heterozygous DIS3 mutations are recurrently observed in approximately 10–20% of patients with multiple myelomas and detected in AML and other cancer types." (PMID 34948199, 2021). "DIS3 mutations have been found in some patients with multiple myeloma (MM), and these patients have a lower median overall survival than other MM patients." (PMID 33585230, 2020). "Delineating the impact of DIS3 perturbation has become of medical importance over the past decade as DIS3 mutations have been identified in roughly 11% of multiple myeloma (MM) patients, particularly within the exonuclease domain." (PMID 30724665, 2019). "Mutations in Dis3, a catalytic subunit of the RNA exosome with separable endonuclease and exonuclease activities, are linked to multiple myeloma." (PMID 30724665, 2019). "Towards this goal, we have phenotypically characterized a yeast strain harbouring a Dis3 mutation (E729K) that is orthologous to a human mutation (E665K) first identified in a myeloma sequencing study." (PMID 30724665, 2019). "In contrast to RB1, the exosome endoribonuclease DIS3 is mutated in ~10% of NDMM and ~75% of these mutations occur in del(13q) myeloma suggesting biallelic loss of DIS3 occurs in most DIS3 mutated myeloma." (PMID 31231360, 2019). "The human protein DIS3 is of interest due to its frequent mutation in multiple myeloma patient cells." (PMID 29802118, 2018). "Global sequencing studies have identified DIS3 as being mutated in a range of cancers, with a considerable incidence in multiple myeloma." (PMID 29802118, 2018). "High-throughput studies have identified that DIS3 is recurrently mutated in different types of cancer such as multiple myeloma (10%) and in acute myeloid leukaemia (AML, 4%)." (PMID 29802118, 2018). "The reduced activity of yeast DIS3 mutants alongside genomic data, that show how tumor cells usually retain only the mutated copy of DIS3, suggest a role for DIS3 as a tumor suppressor in multiple myeloma." (PMID 25925570, 2015). "This raises the possibility that mutation and selection of DIS3 as a driver mutation in myeloma is dependent on deletion of 13q14." (PMID 26193331, 2015). "Perhaps most striking is the finding that DIS3 is recurrently mutated in 11% of multiple myeloma patients." (PMID 26193331, 2015). "Mutations in Dis3 are associated with a number of human cancers including multiple myeloma and acute myeloid leukemia." (PMID 25892215, 2015). "Recent next-generation sequencing efforts have identified somatic mutations in DIS3 in the hematological cancers multiple myeloma (MM) and acute myeloid leukemia." (PMID 25925570, 2015). "Global screens have revealed that mutations or aberrant expression of Dis3 are often associated with human cancers such as multiple myeloma, medulloblastoma, acute myeloid leukemia and melanoma." (PMID 25892215, 2015). "The most striking association between DIS3 and cancer is probably the finding that DIS3 is recurrently mutated in multiple myeloma (MM)." (PMID 26193331, 2015).
multiple myeloma (continued). "Gene expression profiling studies have shown aberrant expression of DIS3 in a small range of different cancers and recently whole genome/whole exome and amplicon sequencing studies have revealed DIS3 to be recurrently mutated in multiple myeloma." (PMID 26193331, 2015). "Mutations in DIS3, which encodes the catalytic component of the RNA exosome in humans, are the fourth most common single nucleotide variation identified in multiple myeloma (∼10% of all newly diagnosed patients)." (PMID 36861343, 2023). "However, the most significant association of DIS3 and human disease is the recurrent loss-of-function mutations in multiple myeloma patients." (PMID 26193331, 2015). "However, additional mechanistic studies are required to understand how mutations in DIS3, and the function of the RNA exosome, could contribute to pathogenesis in multiple myeloma." (PMID 36861343, 2023). "However, how loss-of-function DIS3 mutations are tumorigenic and how they contribute to multiple myeloma pathogenesis remains largely unknown." (PMID 25925570, 2015). "This may be an important consideration when performing knock-down experiments to investigate the role of DIS3 in myeloma development, as DIS3 knock-down is likely to have a different effect within the cell than DIS3 mutations, which probably affect the function of the protein." (PMID 26193331, 2015). "Although DIS3 gene alterations are frequent in multiple myeloma (MM), a PC malignancy, their molecular impact remains poorly understood." (PMID 41286079, 2026). "Recurrent lymphoid CH mutations (in FAT1, KMT2D, MGA, and SYNE1) and myeloma driver gene mutations (in ZFHX3 and DIS3) were found in the dominant clonal and subclonal plasma cell populations." (PMID 40152254, 2025). "The association of isoform 1 with the cancer phenotype is borne out by our results showing that it is the principal transcript in myeloma patient cells, making up ∼80% of total DIS3 protein levels in the 11 patients tested." (PMID 29802118, 2018). "DIS3 is a catalytic subunit of the human exosome complex, containing exonucleolytic (RNB) and endonucleolytic (PIN) domains, recently found mutated in multiple myeloma (MM), a clinically and genetically heterogeneous form of plasma cell (PC) dyscrasia." (PMID 26305418, 2015). "DIS3 mutant organisms rather than knock-down models are likely to provide a better insight into the role of DIS3 in myeloma pathogenesis." (PMID 26193331, 2015). "This article aims to review current knowledge of the structure, mechanisms and functions of DIS3 as well as highlighting the genetic patterns observed within myeloma patients, in order to yield insight into the putative role of DIS3 mutations in oncogenesis." (PMID 26193331, 2015). "Meanwhile, miRNA-125a was reported to have oncogenic potential, which may promote the progression and invasion of gastric cancer through the regulation of EphA2, TAZ, and TEAD2 and myeloma progression through a reduction in DIS3 expression level." (PMID 40282476, 2025). "If DIS3 plays an important role in myeloma progression, we may expect DIS3 mutants to display over-proliferation or de-differentiation, phenotypes more consistent with those observed in tumours." (PMID 26193331, 2015). "A combination of DIS3 and spindle-assembly checkpoint defects may allow cells to progress through the cell-cycle without proper chromosome segregation generating aneuploidy cells which lead to the development of myeloma." (PMID 26193331, 2015). "It is useful to note that there appears to be an accumulation of mutations in the RNB domain of DIS3 but not DIS3L in myeloma, suggesting that inhibition specifically of the exonucleolytic activity of the nuclear exosome is what may facilitate oncogenesis." (PMID 26193331, 2015).
multiple myeloma (continued). "Despite the distinct burden of subclonal mutations, some CH mutations were conservative among MM, AL, POEMS, and MGUS, including lymphoid and myeloid CH mutations, such as those in KMT2D, FAT1, MGA, and SYNE1, and myeloma driver genes like ZFHX3 and DIS3." (PMID 40152254, 2025). "Beyond well-known myeloma genes such as KRAS, NRAS, DIS3, and FAM46C5–8, several other interesting candidate genes emerged." (PMID 31444325, 2019). "Although it is unclear whether these mechanisms work similarly in myeloma cells, AID and/or immunoglobulin expression may confer DIS3-dependent mechanisms specifically in myeloma pathogenesis." (PMID 34948199, 2021). "In contrast, another patient with an NTRK1 fusion, MMRF 2490, had clonal mutations in well-known myeloma tumor suppressors EGR1 and DIS3, meaning that targeting the NTRK1 fusion alone may not have been sufficient." (PMID 32471990, 2020).
acute myeloid leukemia (5 papers, 2015 to 2023). Acute myeloid leukemia (AML) is a group of neoplasms arising from precursor cells committed to the myeloid cell-line differentiation. "Whole genome sequencing studies have identified missense mutations in DIS3 to occur in ~4% (4/106) of Acute Myeloid Leukaemia (AML) patients." (PMID 26193331, 2015).
Wilms tumor (3 papers, 2014 to 2016). An embryonal neoplasm characterized by the presence of epithelial, mesenchymal, and blastema components. "Closest homologues of Sts5 include S. cerevisiae Ssd1, S. pombe Dis3L2, and the human exonuclease Dis3L2, which has been associated with diseases such as Perlman syndrome and Wilm’s tumor, as well as Rrp44/Dis3." (PMID 27474797, 2016). "Therefore, the inactivation of DIS3L2, as reported in Perlman syndrome and in a subset of Wilms tumors, would have entirely different functional consequences for the cell, when compared with the effect of DIS3." (PMID 25925570, 2015).
breast carcinoma (2 papers, 2015 to 2024). "Conclusively, we identified multiple genes, including DIS3, TBP, and EXOC1, as potential dual-effectors that regulate both MHC-I expression and cell survival in breast cancer." (PMID 39408874, 2024). "Further flow cytometry experiments confirmed that knockout of DIS3, TBP, or EXOC1 individually markedly increased MHC-I levels on the cell surface of breast cancer MCF7 cells." (PMID 39408874, 2024). "Furthermore, we verified partially according to KEGG functional enrichment or gene-dependency analysis and figured out multiple genes, including PIP5K1A, NCKAP1, CYFIP1, DIS3, TBP, and EXOC1, as effective gene targets for increasing MHC-I expression in breast cancer." (PMID 39408874, 2024).
colorectal cancer (2 papers, 2015 to 2020). A primary or metastatic malignant neoplasm that affects the colon or rectum. "In support of our predictions, DIS3 is recurrently mutated in blood and skin cancers and has been identified as a candidate oncogene in colorectal cancer." (PMID 32711844, 2020). "This observed overexpression could be due to an amplification of the DIS3 locus, 13q22, frequently observed in colorectal cancer." (PMID 26193331, 2015). "This difference in copy number between colorectal cancer and CLL may suggest a tissue-context dependent role of DIS3 in promoting cancer development." (PMID 26193331, 2015).
melanoma (2 papers, 2015 to 2023). A malignant, usually aggressive tumor composed of atypical, neoplastic melanocytes. "Although DIS3 has been found to be associated with multiple types of cancer including colorectal, melanoma and three types of blood cancers, there is no consensus about whether DIS3 is a tumour suppressor or oncogene." (PMID 26193331, 2015). "In superficial spreading melanoma (SSM) cells, DIS3 has reduced expression compared to normal melanocytes because one chromosomal copy is deleted." (PMID 26193331, 2015).
breast tumors (1 paper, 2015). "Firstly, the DIS3/BORA SAGP is significant and synergistic in terms of patients survival in two independent BC patients cohorts; both gene partners are significantly correlated and activated in basal-like breast tumors." (PMID 26517092, 2015).
cyst (1 paper, 2025). A sac-like closed membranous structure that may be empty or contain fluid or amorphous material. "This is indicative of the role of the DIS3 variant in the process of germline cyst encapsulation and, in turn, somatic support cells of the Drosophila ovary." (PMID 39400047, 2025).
Infertility (1 paper, 2025). "Similar observations have been made in Drosophila whereby germline knockdown (KD) of DIS3 ortholog Dis3 results in complete infertility in female flies and significant atrophy of ovarian structures with no observable oocytes." (PMID 39400047, 2025).
lymphocytic leukemia (1 paper, 2012). "On this note, the closest human homolog to Dis3 is located at 13q21, a chromosomal locus linked to a variety of cancers, including lymphocytic leukemia." (PMID 22853036, 2012).
Lynch syndrome (1 paper, 2026). An autosomal dominant hereditary neoplastic syndrome characterized by the development of colorectal carcinoma and a high risk of developing endometrial carcinoma, gastric carcinoma, ovarian carcinoma, renal pelvis carcinoma, and small intestinal carcinoma. "In addition, the Lynch syndrome samples showed substantial sex-based differences in immune and inflammatory pathways, for example, downregulation of ZG16, DIS3, and WDR43." (PMID 41727057, 2026).
male infertility (1 paper, 2024). The inability of the male to effect fertilization of an ovum after a specified period of unprotected intercourse. "Thus, Dis3 ablation in germ cells disrupts spermatogenesis, resulting in agametic seminiferous tubules in adult testes and male infertility." (PMID 38953252, 2024).
osteosarcoma (1 paper, 2015). A usually aggressive malignant bone-forming mesenchymal neoplasm, predominantly affecting adolescents and young adults. "We hence knocked down DIS3 in human osteosarcoma U2OS cells, in human kidney embryonic HEK-293T cells and in mouse embryonic fibroblast NIH3T3 cells, using an shRNA targeting respectively the DIS3 human (shRNA4) and Dis3 mouse sequence." (PMID 25925570, 2015).
pancreatic cancer (1 paper, 2017). "The pancreatic cancer risk locus rs386772267 suppresses the expression of DIS3 via the loop between rs386772267 and the promoter of DIS3 with an allele-specific TF." (PMID 29149895, 2017).
plasma cell dyscrasias (1 paper, 2015). "In conclusion, these data further support the pathological relevance of DIS3 mutations in plasma cell dyscrasias and suggest that DIS3 may represent a potential tumor suppressor gene in such disorders." (PMID 26305418, 2015).
Premature ovarian insufficiency (1 paper, 2025). Amenorrhea due to loss of ovarian function before the age of 40. "DIS3 variant identified in a patient with premature ovarian insufficiency has reduced capacity to rescue Drosophila ovarian Dis3 knockdown compared to wildtype, suggesting the variant is hypomorphic and the RNA exosome is critical for ovarian function." (PMID 39400047, 2025).
rectal cancer (1 paper, 2012). A primary or metastatic malignant neoplasm that affects the rectum. "In twenty rectal cancer tissues, GPNMB and DIS3 were positively stained in six and five cases, respectively." (PMID 23158542, 2012).
superficial spreading melanoma (1 paper, 2016). A type of melanoma that typically occurs in light-skinned individuals ranging in age from young adults to the elderly. "Superficial spreading melanoma (SSM) and nodular melanoma (NM characteristically express the eight genes GALNT7, DIS3, FGFR1OP, G3BP2, MTAP, SEC23IP, USO1, and ZNF668." (PMID 27322213, 2016).